FAT4 (FAT atypical cadherin 4)
Diseases named in the same sentence as FAT4 in open-access papers (continued):
Sharing a sentence is not in itself a finding about the gene and the disease.
tumor (continued). "According to our results, monitoring of FAT4 mutation in cfDNA may be a substitute for tumor biopsy in stage IV GC." (PMID 36779847, 2023). "Additionally, FAT4 expression was associated with the infiltration of anti-tumor-related immune cells and the expression of immune activators." (PMID 37735184, 2023). "Collectively, these results suggest that FAT4 may exert tumor suppressor effects by promoting the infiltration of tumor-associated immune cells." (PMID 37735184, 2023). "Furthermore, FAT4 expression was associated with markers of tumor-associated macrophages, such as CCL2, CD68, and IL-10." (PMID 37735184, 2023). "FAT4 protein is located to the cell membrane in mammalian cells and is thought to have tumor-suppressive effects; double allele FAT4 inactivation promotes tumorigenicity in mouse mammary epithelial cell lines; however, its role in tumor immunity is unknown." (PMID 37658376, 2023). "The possible elimination of the sub-clone harboring mutations in mTOR, PIK3CA and a FAT4 due to adjuvant chemotherapy could have happened either in the primary tumor or in the metastasis." (PMID 31953485, 2020). "Interestingly, FAT4 downregulation was inversely associated with the tumor grade, and higher repression corresponds to advanced grades." (PMID 32366234, 2020). "Notably, the only gene that was commonly mutated among the two primary HCCs and two IMs was FAT4, which recurrently mutated in several other cancers and possibly acted as a tumor suppressor." (PMID 26672766, 2016). "In addition, we identified FAT4 as a putative tumor suppressor in HCC that was recurrently mutated, significantly down-regulated and had profound functional and prognostic importance." (PMID 26672766, 2016). "Therefore, FAT4 mutation may promote anti-tumor immunity by inducing the variation of tumor-infiltrating immune cells in GC." (PMID 39323626, 2024). "Thus, we speculate that the superior survival in the FAT4 mutation group may be attributed to the anti-tumor immunity induced by high TMB." (PMID 39323626, 2024). "Neither has been explored in their relationship with biological sex differences; however, FAT4 acts as a tumor-suppressor gene with typically lower expression in tumors, while BCOR (BCL6 corepressor gene) drives oncogenic transformation in neural cells." (PMID 40362575, 2025). "In conclusion, we demonstrated that UBE4B not only promotes the growth of GC tumours in vivo but also plays a corresponding role by regulating FAT4 levels." (PMID 40701960, 2025). "Several studies have shown that FAT4 has cancer-inhibiting effects on tumours such as breast cancer, cervical cancer, and GC." (PMID 40701960, 2025). "Research indicates that FAT4 (FAT Atypical Cadherin 4) regulates β-catenin ubiquitination levels, leading to increased anti-tumor immunity." (PMID 39223632, 2024). "FAT atypical cadherin 4 (FAT4) functions as a tumour suppressor and has been detected on the cell membrane of mammalian cells." (PMID 39735605, 2024). "Meanwhile, the downregulation of notable tumor suppressors such as FAT4 and CRNN supports the cancerous characteristics of pepsin." (PMID 39409043, 2024). "The FAT4 tumor suppressor has been shown to restrain tumor growth through modulation of Hippo and Wnt/β-catenin pathways." (PMID 39478125, 2024). "Two private neoepitopes (category T) derived from mutations in the FAT atypical cadherin 4 (FAT4) and Rho GTPase activating protein 26 (ARHGAP26) tumor suppressor genes." (PMID 39840067, 2024). "Aberrant expression of FAT4 assocites with the tumor cell proliferation and immune infiltration in LUAD." (PMID 35770846, 2023). "Intuitively, FAT4 overexpression in immunodeficient BALB/c nude mice reduced tumor size and prolonged survival." (PMID 37658376, 2023).
tumor (continued). "We also validated the relationship between FAT4 and diverse immune marker sets of various tumor‐infiltrating immune cells in LUAD." (PMID 35770846, 2023). "FAT4 (FAT Atypical Cadherin 4) is a member of the cadherin-associated protein family, which has been shown to function as a tumor suppressor by inhibiting proliferation and metastasis." (PMID 37658376, 2023). "Actually, tumor common mutated genes, like TTN, FAT4, and DNAH2, were highly altered in SMC5 mutation samples, respectively, with the alteration frequency of 100%, 88%, and 81% in COAD, and 100%, 89%, and 83% in READ." (PMID 35894836, 2023). "Cell proliferation, clone formation, and immunofluorescence were used to determine the tumor suppressive impact of FAT4 overexpression in vitro, and the findings were confirmed in immunodeficient and immunocomplete mice xenografts." (PMID 37658376, 2023). "Surprisingly, tumor regression from the injection site around the fourth week after injection, indicating that FAT4 overexpression activates antitumor immunity." (PMID 37658376, 2023). "Overexpression of FAT4 combined with jujuboside A (JUA) inhibits the metastasis of LUAD tumor cells through regulating MAPK pathways." (PMID 35770846, 2023). "We found decreased expression of FAT4 protein in tumor tissues compared to those in non‐cancerous lung tissues in LUAD and LUSC." (PMID 35770846, 2023). "The results indicated FAT4 mRNA expression decreased in a majority of NSCLC cohorts (25/27) compared to the corresponding non‐tumor lung tissues (NTL), except for two cohorts (GSE20189 and GSE39345)." (PMID 35770846, 2023). "Functionally, through T cell-mediated cancer cell killing assays and PD-L1/PD-1 binding assays, we demonstrated that FAT4 overexpression in tumor cells significantly activated CTL activity by downregulating PD-L1 levels." (PMID 37658376, 2023). "FAT4 encodes a large protein with extracellular cadherin repeats, EGF-like domains, and laminin G-like domains that play a role in tumor suppression and planar cell polarity." (PMID 37273692, 2023). "Accumulating evidence suggests that FAT4 downregulation is involved in the pathogenesis of multiple malignancies, is inversely correlated with tumor grade, and exerts tumor-suppressor effects." (PMID 37735184, 2023). "FAT4 is a conserved member of the cadherin superfamily, which is involved in cell-to-cell adhesion, capable of suppressing tumor growth through Hippo signaling activation, as well as activating the Wnt-β catenin signaling." (PMID 35392220, 2022). "Functional analysis using RNAi-mediated knockdown of FAT4 revealed an increased cancer cell growth and proliferation, suggesting the putative tumor suppressor role of FAT4 in hepatocellular carcinoma cancer." (PMID 36051999, 2022). "Western blotting detected that YFJDT also upregulated FAT4 in the tumor tissue and A549 cells and downregulated the expression of vimentin." (PMID 35132327, 2022).
tumor (continued). "For survival analysis, the Kaplan-Meier method was used to analyze the correlation between FAT4 and tumor prognosis." (PMID 36051999, 2022). "The survival analysis results suggested the expression level of FAT4 in different tumor types is of great significance to the survival prognosis of cancer patients." (PMID 36051999, 2022). "Our study summarized and analyzed the antitumor effect of FAT4 in different tumors comprehensively, which aided in understanding the role of FAT4 in tumorigenesis from the perspective of clinical tumor samples." (PMID 36051999, 2022). "By analyzing the expression levels of FAT4 in tumor tissues at different stages, we found that FAT4 expression was different in different stages of BLCA, KIRC, and BRCA." (PMID 36051999, 2022). "For example, mutations in the known tumor suppressors FAT1 and FAT4 occurred only in patients S1 and S5." (PMID 36618022, 2022). "It has been also associated with poor prognosis in GC patients and in vitro and in vivo experiments found that FAT4 knockdown increases tumor growth and metastasis, mediated by the Wnt/β-catenin signaling pathway." (PMID 33525650, 2021). "We identified SNVs in the cadherin repeat domains of FAT family genes, i.e., FAT1 and FAT4 in 21% samples, which are functionally characterized as tumor suppressor genes in multiple cancers including ESCC." (PMID 32974170, 2020). "In this study, the tumor suppressor role of FAT4 was shown to be mediated by the regulation of β-catenin activity." (PMID 32366234, 2020). "The adhesion molecule, FAT4, has a tumor suppressor function with a critical role in the epithelial-to-mesenchymal-transition (EMT) and anti-malignant growth in several cancers." (PMID 32366234, 2020). "FAT4 was identified as a tumor suppressor in mouse mammary epithelial cell line and triple-negative breast cancer." (PMID 32366234, 2020). "A previous study found that overexpression of FAT4 promotes cell cycle, proliferation, invasion and migration of certain cancers and inhibits tumor cell apoptosis." (PMID 33063118, 2020). "Functional analysis using RNAi-mediated knockdown of FAT4 revealed an increased cancer cell growth and proliferation, suggesting the putative tumor suppressor role of FAT4 in HCC." (PMID 31395065, 2019). "Taken together, knockdown of FAT4 promotes cell growth and proliferation indicating the putative tumor suppressor role of FAT4 in HCC." (PMID 31395065, 2019). "After gaining abundant acknowledgement of the in vitro effects of FAT4, we sought to further elucidate the tumor suppressor role of FAT4 during tumor growth in vivo." (PMID 30832706, 2019). "FAT4 staining was exclusively cytoplasmic in normal gastric epithelial cells and few cases of tumor cells." (PMID 29435168, 2018). "Immunohistochemical analysis showed lower FAT4 expression in tumor tissues from GC patients than in normal gastric epithelium." (PMID 29435168, 2018). "We demonstrated the critical role of FAT4 in GC progression by showing that FAT4 knockout BGC-823 cells showed increased tumor growth and progression, both in vitro and in vivo." (PMID 29435168, 2018). "Our data is in accordance with previous studies that demonstrate the tumor suppressive role of FAT4 in various cancers." (PMID 29435168, 2018). "Methylation-specific PCR analysis showed increased FAT4 promoter methylation in GC tumor tissues and cell lines." (PMID 29435168, 2018).
tumor (continued). "Lower FAT4 expression correlated with tumor size, tumor invasion depth (T Grade) and vascular invasion (P<0.05)." (PMID 29435168, 2018). "Among the 60 paired HCC and normal tissue samples, 70% (42/60) of the tumor showed down-regulation of FAT4 mRNA by Qualitative RT-PCR analysis (P = 0.005)." (PMID 26672766, 2016). "Here, we show that FAT4 mRNA expression is repressed in response to actin dynamics during Src-induced tumor transformation of MCF-10A cells." (PMID 25679223, 2015). "FAT4 (protocadherin fat 4), a member of the cadherin super-family, is a key component in the Hippo signaling pathway, playing a candidate tumor suppressor role in cancer." (PMID 26352260, 2015). "Based on their biological roles in the context of cancer, it appears that the inhibition of CD200 and FAT4 would be effective in reducing tumor volume." (PMID 24944582, 2014). "One of the mechanisms identified for the miR-31 mediated increasing cell motility was through direct repression of a novel tumor suppressor and inhibitor of migration, FAT4; moreover, a reduction of FAT4 enhanced EC mobility." (PMID 25421888, 2014). "FAT1 and FAT4 suppress tumor growth through Hippo signaling activation, while FAT1 promotes tumor migration through actin polymerization at lamellipodia and filopodia." (PMID 23076869, 2012). "FAT1 and FAT4 suppress tumor growth via activation of Hippo signaling, whereas FAT1 promotes tumor migration via induction of actin polymerization." (PMID 23076869, 2012). "Together, these facts indicate that FAT1 is tumor suppressive or oncogenic in a context-dependent manner and that FAT4 is preferentially tumor suppressive." (PMID 23076869, 2012). "FAT1, FAT2, FAT3 and FAT4 are human homologs of Drosophila Fat, which is involved in tumor suppression and planar cell polarity (PCP)." (PMID 23076869, 2012). "FAT1 is tumor suppressive or oncogenic in a context-dependent manner, while FAT4 is tumor suppressive." (PMID 23076869, 2012). "Tumor growth is inhibited by re-introduction of Fat4 gene into cells derived from the cutaneous tumor." (PMID 23076869, 2012). "UBE4B was highly expressed in most tumour samples, whereas FAT4 was expressed at low levels." (PMID 40701960, 2025). "It has been verified that FAT4 could affect tumor metastasis and regulate TMB and microsatellite instability to influence the immunotherapy response through calcium signaling pathways and chemokine signaling pathways." (PMID 41019085, 2025). "To further explore the influence of FAT4 mutation on the abundance of different tumor-infiltrating immune cells, we employed the CIBERSORT algorithm to estimate the fraction of 22 immune cells in each tumor sample." (PMID 39323626, 2024). "Consistent with previous findings, we found that it was decreased in several tumors, suggesting that FAT4 may exhibit tumor suppressor effects in various tumors." (PMID 37735184, 2023). "Therefore, future experiments should investigate the specific mechanisms by which FAT4 regulates immune cell infiltration to identify novel targets for tumor immunotherapy." (PMID 37735184, 2023). "Moreover, the FAT4 expression included multiple immunological components to promote an immunosuppressive tumor microenvironment (TME)." (PMID 35770846, 2023). "FAT4 is a cadherin-related gene and is considered a tumor suppressor in multiple human cancers." (PMID 37006317, 2023). "And FAT4 overexpression in U14 cells enhanced T cell-mediated tumor cell killing." (PMID 37658376, 2023). "About the remaining genes, FAT4 was upregulated in Xenopus tumor and downregulated in human cancer." (PMID 37580380, 2023). "FAT4 Potential functions and mechanisms in tumor progression and tumor immunology remained unclear." (PMID 36051999, 2022).
tumor (continued). "We analyzed the expression of FAT4 in tumor and normal tissues." (PMID 36051999, 2022). "FAT4 expression in most tumor tissues was lower than in corresponding control tissues." (PMID 36051999, 2022). "Of these, we found that heterozygous missense mutations in four genes—FAT4, FAT1, FAT3, and ERCC2—were predicted to be deleterious and also detected by tumor RNA sequence data, indicating that the mutant alleles were expressed in the tumor." (PMID 33733072, 2021). "As FAT4 and miRNAs could affect the proliferation and migration of tumor cells, the current study aimed to determine the specific miRNA regulating FAT4 expression in CRC." (PMID 33063118, 2020). "In summary, our data reveal that FAT4 is a tumor suppressor in CRC." (PMID 30832706, 2019). "We further assessed the tumor autophagy-promoting mechanism of FAT4 by decreasing the activity of the PI3K/AKT/mTOR signaling pathway in CRC and by inhibiting the EMT through reductions in the levels of proteins involved in the PI3K/AKT/GSK-3β signaling pathway." (PMID 30832706, 2019). "Moreover, an increase in FAT4 leads to a reduction in xenograft tumor growth in vivo, whereas the opposite outcome was obtained with FAT4 knockdown." (PMID 30832706, 2019). "In addition, some of the mutation occurrences were tumor type-specific, e.g., PIK3CA mutations showed co-occurrence with FAT4 mutations with a high frequency in BLCA, but mainly co-occurred with PTEN mutations in UCEC." (PMID 29697365, 2018). "Moreover, xenografts of BGC-823 cells with FAT4 knockdown showed enhanced tumor growth and metastasis in nude mice." (PMID 29435168, 2018). "We observed gradual decrease in FAT4 expression as tumor progressed from a non-metastatic state to tumor associated with lymph node and distant metastasis." (PMID 29435168, 2018). "FAT4 expression was detected in 263 (58.6%) out of 449 GC tumor samples analyzed." (PMID 29435168, 2018). "FAT4 acts as a putative tumor suppressor that is frequently inactivated in human HCC." (PMID 26672766, 2016). "FAT4 mutation has been found to be significantly correlated with high TMB in GC samples, which may facilitate the exposure of neoantigens to the immune system, eliciting an enhanced anti-tumor immune response." (PMID 39323626, 2024). "Moreover, the OS of patients with HCC and high FAT4 expression was prolonged, further suggesting that FAT4 has tumor suppressor effects in HCC and may serve as a novel prognostic biomarker." (PMID 37735184, 2023). "Thus, FAT4 may have a tumor suppressor role in HCC by inhibiting tumor cell invasion and metastasis." (PMID 37735184, 2023). "FAT4 might influence the efficacy of immunotherapy via tumor burden and microsatellite instability." (PMID 36051999, 2022). "Through Gene Expression Analysis, we speculated that FAT4 was a tumor suppressor gene." (PMID 36051999, 2022). "In addition, the function of FAT4 in vivo was assessed using a tumor xenograft model." (PMID 30832706, 2019). "Furthermore, throughout the growth process, the average tumor weight was typically obtained in the groups with reduced FAT4 expression, whereas the FAT4-overexpressing HCT116 and LOVO cells yielded tumors with relatively lighter weights throughout the growth process." (PMID 30832706, 2019). "Interestingly, our multiregional mRNA expression data showed that 18.2% (4/22) of HCC cases showed intratumor heterogeneous expression of FAT4 (i.e., co-existence of up- and down-regulation), while the remaining cases displayed homogeneous up- or down-regulation within each tumor." (PMID 26672766, 2016). "Notably, we identified FAT4 as a potential driver in hepatocarcinogenesis and tumor progression." (PMID 26672766, 2016).